EGFR (epidermal growth factor receptor)
Diseases named in the same sentence as EGFR in open-access papers (continued):
Sharing a sentence is not in itself a finding about the gene and the disease.
lung cancer (continued). "The combination of Notch inhibitors with EGFR inhibitors, gefitinib or osimertinib, was found to be effective in EGFR tyrosine kinase inhibitor-resistant lung cancer." (PMID 36382054, 2022). "In this study, we propose LPIN1 as a factor regulating gefitinib resistance in EGFR-mutant lung cancer cells, which upon depletion, results in synthetic lethality with gefitinib treatment." (PMID 35565351, 2022). "As a part of the transmembrane receptor tyrosine kinases (RTKs) family, EGF receptor (EGFR) appears to be highly expressed and constitutively activated in multiple cancer types, such as lung cancer and glioblastoma." (PMID 35931120, 2022). "In lung cancer model, its activation is sufficient to cause resistance to EGFR-TKI, while its chemical inhibition reduces cell proliferation under EGFR-TKI and increases apoptosis in vitro and in a PDX model." (PMID 35681591, 2022). "The three tested cannabinoids were potent growth inhibitors and showed a dose-dependent inhibition in the EGFR-positive epidermoid carcinoma A431 and lung cancer A549 ​cell lines." (PMID 36568260, 2022). "A systemic application of EGFR inhibitors, e.g. during lung cancer therapy, is frequently accompanied by cutaneous adverse effects, including an acceleration of keratinocyte differentiation and an impairment of the epidermal barrier." (PMID 34991250, 2022). "For example, miR-7 suppresses the proliferation of lung cancer cells by targeting the epidermal growth factor receptor (EGFR)." (PMID 36555120, 2022). "Previous studies have shown that IDH‐mutant proteins can inhibit TET2 activity, while TET2 knockdown confers resistance to EGFR inhibitors in lung cancer cells." (PMID 35526267, 2022). "For example, it has been previously shown that combined DNA and RNA analyses from plasma result in higher detection rates of EGFR mutant lung cancer." (PMID 36451702, 2022). "Recent studies have indicated that EGFR is a target of immunotherapy for tumors including lung cancer and glioblastoma multiforme." (PMID 35665333, 2022). "A total of 4,404 patients were initially identified who had been pathologically diagnosed with lung cancer and had undergone the molecular (EGFR or PD-L1) test." (PMID 35250988, 2022). "Treatment of EGFR-mut lung cancers with tyrosine kinase inhibitors (TKI) that specifically target the EGFR-mut function results in a complete or partial response in about 75% of patients." (PMID 35061724, 2022). "Data from 162 patients with resected brain metastases originating from lung cancer (70 with mutant EGFR, 92 with wild-type EGFR) were retrospectively analyzed." (PMID 35912248, 2022). "Second-generation irreversible TKIs were initially developed for patients with EGFR-mutated tumors and represented the first attempts to target HER2 in lung cancer." (PMID 36294789, 2022). "Crosstalk between the M3 receptor and EGFR was suggested in lung cancer, enhancing processes such as proliferation, migration, and invasion due to ACh activity." (PMID 35565451, 2022). "EGFR is another important driver gene in lung cancer with multiple drugs targeting its protein products (EGFR inhibitors) being approved by the FDA." (PMID 35016696, 2022). "This is because EGFR-related targeted drugs have played an important role in the diagnosis and treatment of lung cancer." (PMID 35663041, 2022). "In an EGFR-TKIs-resistant lung cancer mouse model, the HH inhibitor, LDE225 (Sonidegib), in combination with gefitinib significantly inhibited tumor growth than gefitinib alone, completely inhibiting the phosphorylation of PI3K/AKT and MAPK signaling." (PMID 35433472, 2022).
lung cancer (continued). "Several receptors, including the Epidermal Growth Factor (EGFR) receptor, are overexpressed in lung cancer, including HER-1, HER-2/neu, HER-3, and HER-4." (PMID 36085575, 2022). "Treatment of EGFR mutant lung cancers with EGFR-TKIs effectively inhibits tumor progression and prolongs progression free survival (PFS) in patients with NSCLC compared with standard chemotherapeutic agents." (PMID 35620280, 2022). "We chose NF1 as the downstream target for validation, as NF1 has previously been associated with lower urinary tract dysfunction and resistance to EGFR inhibition in lung cancer." (PMID 35130920, 2022). "MET amplification has been observed in lung cancer patients treated with the EGFR inhibitors gefitinib and erlotinib, and treatment of gefitinib-resistant tumors with the Met inhibitor crizotinib is effective in the clinic for these patients." (PMID 35249128, 2022). "The mutational constitutive activation of the kinase domain of EGFR is linked to non-small cell lung cancer (NSCLC), accounting for 80% of lung cancer." (PMID 35744964, 2022). "In view of the high incidence of lung cancer, there are a lot of NSCLC-diagnosed patients found to harbor rare EGFR mutations." (PMID 35744964, 2022). "The survival between single lung cancer and LCF were significantly different at stage 1 and 4 with EGFR mutations (p < 0.001)." (PMID 36233811, 2022). "Epidermal growth factor receptor (EGFR) is a well-known oncogenic tyrosine kinase activated in lung cancer." (PMID 35625561, 2022). "A cross-talk between ERs- and EGFR-related signaling pathway was well established in breast cancer and lung cancer." (PMID 35664735, 2022). "The introduction of epidermal growth factor receptor (EGFR)-tyrosine kinase inhibitors (TKIs) has revolutionized the treatment of lung cancer." (PMID 36139582, 2022). "On lung cancer, one of the most relevant oncogenes and a predictive biomarker with clinically approved therapies is EGFR." (PMID 35330479, 2022). "Combination therapies with 3rd G EGFR-TKIs and MEK inhibitors have been developed for lung cancers with EGFR mutations (NCT02143466)." (PMID 35463360, 2022). "Previous studies suggest that TRAF4 promotes epidermal growth factor receptor (EGFR) activation in non‐small cell lung cancer (NSCLC)." (PMID 35748027, 2022). "We have developed a machine learning-based method for identifying the status of EGFR mutations in NSCLC which can provide radiologists with a quantitative and intuitive method to determine the type of gene mutation in lung cancer." (PMID 36230590, 2022). "ND-conjugated specific EGFR antibody can apply for targeting EGFR and monitoring tumorigenesis during lung cancer progression and therapy." (PMID 36678740, 2022). "Concomitantly with the introduction of osimertinib in the clinical practice, cross-resistance has been reported between gefitinib and irreversible EGFR-TKIs in human lung cancer cells." (PMID 35814399, 2022). "As a model, the in vivo imaging of electron transfer in EGFR signaling pathways was assessed in a mouse with lung cancer." (PMID 35105871, 2022). "On this account, ncRNAs are pyramidally utilized to illustrate the tumorigenesis and progression of malignancies, creating the conditions for in-depth research on the mechanisms of EGFR TKI-resistant lung cancer." (PMID 36139582, 2022). "Molecular-targeted medicines, such as EGFR-TKIs, have considerably improved the outcome of advanced lung cancer patients compared to standard therapy." (PMID 36300191, 2022). "Another major regulator of IL-8 release in lung cancer is the MEK/ERK pathway, which is constitutively active in some cell lines with mutations in Ras or EGFR pathways, or activated by growth factors." (PMID 36522309, 2022). "Here we undertake a comprehensive systematic validation of all fusion genes detected by the DNA-based hybrid capture NGS OncoPanel in EGFR-mutant lung cancer, as underappreciated mediators of TKI resistance." (PMID 36153311, 2022).
lung cancer (continued). "Despite the success of EGFR TKIs in EGFR mutant lung cancer, all patients eventually develop acquired resistance to these therapies." (PMID 35543090, 2022). "Another anti-EGFR monoclonal antibody, nimotuzumab, has shown promising results in a variety of solid tumors, such as head and neck neoplasm, non–small cell lung cancer, neuroglioma, and pancreatic cancer." (PMID 35898885, 2022). "BIQO-19 exhibited broad and effective antiproliferative activity against all tested lung cancer cell lines, including EGFR-TKI-resistant NSCLC cells." (PMID 35745617, 2022). "A patient who underwent PBT for stage I lung cancer and emergency salvage lung resection for massive haemoptysis also survived for almost 2 years with pleural dissemination, receiving EGFR–TKI with almost complete remission." (PMID 35253874, 2022). "The results indicated that lung cancer patients with higher ADAMTS8 levels among wild-type EGFR or low PD-L1 groups survive longer than those with lower levels do." (PMID 35743687, 2022). "In this study, we proposed a prediction model based on ResNet deep learning models to predict EGFR mutation status using non-invasive 18F-FDG PET/CT images and clinical data of patients with lung cancer." (PMID 36300191, 2022). "There are two ongoing phase I clinical trials in lung cancer of C-X-C chemokine receptor type 5 modified EGFR-targeted CAR-T cells (NCT04153799, NCT05060796)." (PMID 35720364, 2022). "Recent studies have shown that NF-κB activation in lung cancers treated with EGFR inhibitors promotes the survival of tumor cells and induces the development of drug resistance." (PMID 35740609, 2022). "Extensive efforts in recent decades have attempted to combat lung cancer, particularly through the development of epidermal growth factor receptor (EGFR) inhibitors—a milestone in NSCLC targeted therapy." (PMID 35188360, 2022). "With the advent of genomic medicine, EGFR-positive lung cancer was found to represent about 13–47% of LUAD patients." (PMID 36304306, 2022). "EGFR‐TKI‐targeted therapy is the most widely used clinical treatment for lung cancer; however, drug resistance remains a significant challenge." (PMID 35838331, 2022). "This suggests that the increase in CXCL10 in the tumor microenvironment during EGFR-TKI treatment paradoxically increases oncogenic pathway activity in EGFR-mutant lung cancer through Src-NF-κB-HIF-1α signaling." (PMID 36612121, 2022). "So far, lung cancer patients, with EGFR-TKI resistance, are difficult to be treated by targeted therapy, and the combination regimen will also be affected by adverse reactions and the patients’ physical conditions." (PMID 35463301, 2022). "Surgical resection of the lung for biopsy under general anesthesia was performed in 8.9% of the patients, whereas cytology of pleural effusion or sputum was used in 6.7% of the patients for lung cancer diagnosis and EGFR testing." (PMID 35681723, 2022). "Molecular targeted therapies, such as EGFR-TKIs, can be expected to promote improvement from the lung cancer-induced deterioration of the physical condition of patients due to their high response rate." (PMID 36522630, 2022). "Tumor heterogeneity also promotes the resistance of lung cancer to epidermal growth factor receptor (EGFR) tyrosine kinase inhibitors (TKIs)." (PMID 35668934, 2022). "In Palbociclib resistant lung cancer cells, an increased activation of several receptor kinases was observed, such as epidermal growth factor receptor (EGFR), ephrin type-A receptor 1/2 (EphA1/2) and fibroblast growth factor receptor (FGFR)." (PMID 35712501, 2022). "Lung cancer cells harboring wild-type EGFR (A549) and T790M mutant EGFR (H1975) are more sensitive to Afatinib than to Gefitinib." (PMID 34661759, 2022). "In resistant-EGFR-TKIs lung cancer cells, aberrant activations of the HH pathway are frequently observed." (PMID 35433472, 2022).
lung cancer (continued). "Strategies that lead to acquired EGFR-TKI resistance, such as HGF, MET amplification, and EGFR T790M, also promote immune escape in lung cancer by upregulating the expression of PD-L1." (PMID 35840984, 2022). "The first-generation EGFR-TKIs (include Gefitinib and erlotinib) are applied to the treatment of lung cancer." (PMID 36386184, 2022). "The result is also consistent with the recent report that demonstrated IL-1β-induced tissue factor expression via EGFR-dependent and -independent mechanisms in lung cancer A549 cells." (PMID 35740292, 2022). "Retrospective analysis of the data of patients diagnosed with in nonsmall cell lung cancer (NSCLC) by EGFR gene testing was carried out in the Department of Thoracic Surgery, Jinan Central Hospital." (PMID 35422977, 2022). "Prior to our study, there were almost no in vivo studies on the function of tumor suppressor genes in oncogenic EGFR-driven lung cancer." (PMID 35252550, 2022). "Immune escape ability in addition to the EGFR signaling activation would be a crucial factor for the progression of chromothriptic lung cancers." (PMID 35710642, 2022). "In a retrospective study of 37 BRAF-mutated lung cancer patients, ORR was 24% and PFS was 3.1 months, which was slightly better than that of patients with EGFR mutation." (PMID 35407463, 2022). "For instance, blocking the epidermal growth factor receptor leads to an increase in the number of lung cancer stem cells that are dependent on NOTCH signaling." (PMID 36382054, 2022). "Adequate data were available for pooled analyses of two additional types of systemic treatment, namely treatment with EGFR-TKIs in lung cancer and treatment with immunotherapy using PD-1 or PD-L1 inhibitors." (PMID 36077654, 2022). "Nevertheless, insufficient research on ncRNAs involved in the NF-κB pathway makes it difficult to clarify their relationship with EGFR TKI-resistant lung cancer and further study is urgently needed to illustrate their underlying mechanisms." (PMID 36139582, 2022). "Our analysis of lung cancer context-specific interaction networks of hub genes revealed that deregulated expressions of EGFR/MAP2K1/mTOR/TEAD1/YAP1 in lung cancer mediated abnormal expressions of 151 genes in total in 154 cancer-mediated interactions." (PMID 35655775, 2022). "The genomic alteration/mutation analysis of 11 hub-DEGs revealed that the EGFR, MYC, and CHEK1 genes had 12%, 8%, and 1.3% genomic alteration/mutation over the four lung cancer studies." (PMID 35632527, 2022). "Recent studies report that the blockade of TGF-β/TβR, Wnt/β-catenin, and AXL/Gas6 signaling can potentially reduce the EGFR-TKI resistance in lung cancer A549, HCC827, and PC9 cell lines." (PMID 36547898, 2022). "Exon 20 insertion mutations within the EGFR gene are a much rarer genomic event across tumor types, reported in 0.35% of cancers, and 6% of EGFR-mutant lung cancers." (PMID 35785671, 2022). "ICI treatment has been approved for lung cancer, but it has been reported that ICI treatments are less beneficial in EGFR‐mutated NSCLC, and patients with EGFR‐mutated tumors have been excluded from most clinical studies." (PMID 34904383, 2022). "Our data advocates for testing this novel combination of anti‐tumor agents in the clinic as a new strategy for inhibiting EGFR‐driven lung cancer progression." (PMID 35861366, 2022). "Genetic testing for advanced nonsmall cell lung cancer (NSCLC) includes EGFR, ALK, ROS1, BRAF, MET, HER-2, RET, NTRK1/2/3, PI3K, and PD-L1." (PMID 35368895, 2022). "Epidermal growth factor receptor (EGFR)-mutant lung cancer is known to have an immune-deprived microenvironment characterized by a low tumor mutation burden, increased immunosuppressive cytokines, and increased regulatory T (Treg)-cell infiltration." (PMID 36612121, 2022). "Here, we show a carbon-based nanoprobe, nanodiamond (ND), which can be applied for targeting EGFR and monitoring tumorigenesis of human lung cancer cells in vitro and in vivo." (PMID 36678740, 2022).
lung cancer (continued). "This highlights the potential selectivity of the combined targeting of STYK1 and EGFR for EGFR-mutant lung cancer cells." (PMID 35840561, 2022). "Preclinical studies have indicated that the dual inhibition of the PIK3CA and EGFR pathways demonstrates synergistic cell killing in head, neck and lung cancer models." (PMID 35158773, 2022). "This review summarizes the potential mechanisms of noncoding RNAs (ncRNAs) in EGFR TKI-resistant lung cancer and their clinical applications." (PMID 36139582, 2022). "A previous study on the effects of different muscarinic agonists on lung cancer proposed the activation of the EGFR/PI3K/AKT pathway due to M3 activation with partial participation of matrix metallopeptidases (MMPs), but the full mechanism is still unclear." (PMID 35565451, 2022). "In lung cancer, all tumor types being treated were non-small cell lung cancer and the patients received standard cytotoxic chemotherapy (38.9%) or EGFR-TKI (61.1%)." (PMID 35402275, 2022). "A study showed that the fourth-generation of EGFR TKIs, EAI045 in combination with cetuximab is effective in mouse models of lung cancer with EGFR L858R/T790M/C797S mutations." (PMID 36508072, 2022). "The authors demonstrated specific targeting to EGFR-expressing lung cancer cells in vitro, which, in concomitance with NIR irradiation, increases the release of curcumin, thus potentiating its effect." (PMID 35626078, 2022). "Accordingly, increased production of stromal HGF was detected in the stroma of lung cancer patients upon the emergence of resistance to EGFR TKIs, thus corroborating the clinical relevance of the reported findings." (PMID 36324182, 2022). "Previous studies have shown that miR-145 can affect the proliferation and invasion of lung cancer cells by participating in the regulation of c-Myc, EGFR, and nudix hydrolase 1 expression." (PMID 36338717, 2022). "It is well established that lung cancer patients harbour many driver gene mutations, such as K-ras, EGFR, EML4-ALK, and CLIP1-LTK, which contribute to the initiation and progression of lung cancer." (PMID 35574342, 2022). "Targeting of AREG has been considered for other cancers, for example AREG siRNAs reduced EGFR activation in hepatocellular carcinoma cell lines and lung cancer cells, which led to decreased growth and increased sensitivity to anti-EGFR targeted therapy." (PMID 35993275, 2022). "Our findings indicate that autocrine and paracrine activations of the CXCL10/CXCR3 pathway contribute to early EGFR-TKI resistance in EGFR-mutant lung cancer." (PMID 36612121, 2022). "Taken together, those results suggested that CAFs produced Kyn to facilitate lung cancer cells proliferation and EGFR TKIs resistance." (PMID 35831824, 2022). "In another genomic study of BM of various origin, several potentially actionable genomic alterations were associated with lung cancer BM, including AKT1, AURKA, CDK6, EGFR, MEK1, MET, and PIK3CA gene amplifications and CDKN2A deletions." (PMID 36561283, 2022). "Previous studies have shown that PD-L1 TPS ≥50% in lung cancer rarely overlaps with driver oncogenes such as epidermal growth factor receptor and anaplastic lymphoma kinase (ALK)." (PMID 35984185, 2022). "As a result, this subfamily of chemokines has an impact on a variety of lung disorders, ranging from allergic rhinitis to tuberculosis and lung cancer, while impacting critical signaling pathways such as NF-κB, EGFR, and RSK1/2/AKT/ERK." (PMID 36164329, 2022). "The antiproliferative activity of quinazolin-4(3H)-one derivatives was evaluated in various lung cancer cell lines, including EGFR-TKI-resistant NSCLC cell lines." (PMID 35745617, 2022).